ENG (endoglin)
Diseases named in the same sentence as ENG in open-access papers (continued):
Sharing a sentence is not in itself a finding about the gene and the disease.
hepatocellular carcinoma (30 papers, 2006 to 2025). A malignant tumor that arises from hepatocytes. "For example, carotuximab (TRC105), an anti-endoglin monoclonal antibody, has shown promising activity in combination with sorafenib in a phase 1b/2 clinical trial of patients with treatment naïve hepatocellular carcinoma." (PMID 31444620, 2019). "From tumor research we know that the serum level of endoglin is significantly elevated in people with metastatic cancer and primary tumors such as hepatocellular carcinomas." (PMID 26034672, 2014). "Endoglin (CD105) has been considered a prognostic marker for hepatocellular carcinoma (HCC), and widely used as an appropriate targeting for antiangenesis therapy in some cancers." (PMID 17608955, 2007). "Also, high endoglin expression correlated with a worse prognosis in various human solid tumors, including lung, colorectal, prostate, and hepatocellular cancers." (PMID 33995664, 2021). "This review summarizes the current data concerning the role and signalling pathways of endoglin in hepatocellular carcinoma development and progression, and provides an overview of the strategies available for a specific targeting of CD105 in anti-angiogenic therapy in HCC." (PMID 30563158, 2018). "ENG is overexpressed in hepatocellular carcinoma (HCC) micro vessels because HCC is characterized by neovascularization by tumor cells." (PMID 36296203, 2022). "In addition, human HSC LX2 cells and hepatoma cell line HepG2 could express the full length of endoglin and direct endoglin to exosomes, requiring N-glycosylation." (PMID 33809908, 2021). "Similarly, magnetic endoglin-specific aptamer nanoprobes based on modified magnetic carboxymethyl chitosan (CMCS) nanoparticles (aptamer-Fe3O4@CMCS) were generated to target subcutaneous H22 hepatocellular carcinomas in mice." (PMID 33946583, 2021). "For hepatocellular carcinomas (HCC), it has been shown that endoglin expression on HCC cells promotes metastasis in a vascular endothelial growth factor (VEGF)-dependent manner." (PMID 32059544, 2020). "HepG2 cells, an endoglin-negative human hepatoma cell line, showed only 0.44% endoglin expression, which was significantly different from that of hepatocytes in patient sera induction group (p = 0.077), but not from hepatogenic cocktail induction group (p = 0.026)." (PMID 24642599, 2014).
juvenile polyposis (29 papers, 2013 to 2025). "MADH4 variants cause juvenile polyposis/HHT overlap syndrome, while GDF2 encodes BMP9, which can bind to endoglin protein and ALK1 protein, leading to overlapping phenotypes of HHT1 and HHT2." (PMID 40933708, 2025). "Endoglin (ENG), activin A receptor type II-like 1 (ACVRL1/ALK1), and SMAD4 mutations cause HHT1 (OMIM 187300), HHT2 (OMIM 600376), and the combined Juvenile Polyposis/HHT (JP/HHT) syndrome (OMIM 175050), respectively." (PMID 39062925, 2024). "Three genetic mutations have been identified: ENG (HHT1); ACVRL1 (HHT2); and more rarely, SMAD4 (found in HHT associated with juvenile polyposis syndrome), however several hundred different mutations have been described." (PMID 31174568, 2019). "One patient with mutations in both ENG and ACVRL1 genes was identified, as were two SMAD4-mutated patients suffering from the overlapping juvenile polyposis-HHT syndrome." (PMID 30251589, 2018). "Single mutations are detected in Endoglin (ENG; HHT1) (MIM # 131195), Activin Receptor-Like Kinase 1 (ACVRL1/ALK1; HHT2) (MIM # 601284), or MADH4/SMAD4 (JHPT, a combined syndrome of juvenile polyposis and HHT)." (PMID 26176610, 2015). "HHT is transmitted as an autosomal dominant condition due to a single mutation in Endoglin (ENG; HHT1), Activin Receptor-Like Kinase 1 (ACVRL1/ALK1; HHT2), or MADH4/SMAD4 (JHPT, a combined syndrome of juvenile polyposis and HHT)." (PMID 24267784, 2013). "In 90% of patients with a definite clinical diagnosis of HHT, a mutation is identified in one of these three genes: endoglin (ENG, HHT type 1), activin receptor-like kinase-1 (ACVRL1, HHT type 2), and Mothers against decapentaplegic homolog 4 (SMAD4, juvenile polyposis–HHT overlap syndrome)." (PMID 39597796, 2024). "In 96% of patients with a definite clinical diagnosis of HHT, a mutation is identified in one of these 3 genes: endoglin (ENG, HHT type 1), activin receptor-like kinase-1 (ACVRL1, HHT type 2), and Mothers against decapentaplegic homolog 4 (SMAD4, juvenile polyposis–HHT overlap syndrome)." (PMID 38492037, 2024). "Pathogenic variants in the ENG and ACVRL1 genes result in different HHT types, commonly referred to as HHT1 and HHT2, respectively Pathogenic variants in the SMAD4 gene give rise to a combined syndrome of HHT and juvenile polyposis (JP): the JP-HHT syndrome." (PMID 35628811, 2022). "Genetic diagnosis is based on the identification of a mutation in the transforming growth factor-beta (TGF-β) signaling pathway genes: Endoglin (ENG), activin receptor-like kinase 1 (ACVRL 1), or SMAD4 characterized by the juvenile polyposis syndrome (JPS) usually associated with HHT." (PMID 31971937, 2020). "Endoglin (ENG, chromosome 9q34), activin A receptor type II-like 1 (ACVRL1/ALK1, chromosome 12q13), and SMAD4 (chromosome 18q21) mutations cause HHT1 (OMIM 187300), HHT2 (OMIM 600376), and the combined Juvenile Polyposis/HHT (JP/HHT) syndrome (OMIM 175050), respectively." (PMID 25674101, 2015). "The two most commonly mutated genes are endoglin (ENG or HHT1) and activin A receptor type II-like 1 (ALK-1 or HHT2), with SMAD4 mutations reported in a small subset of patients, most of whom also have juvenile polyposis." (PMID 25928712, 2014). "Mutations in three genes have been found to be responsible for HHT: the endoglin (ENG) gene on chromosome 9, the activin-receptor-like kinase 1 (ACVRL1) gene on chromosome 12, and the SMAD4 gene on chromosome 18 (mutations also lead to juvenile polyposis)." (PMID 24603803, 2014). "Mutations in ENG were identified in 31 patients (55%), mutations in ACVRL1 were identified in 17 patients (30%), and one patient had a mutation in SMAD4 and presented with juvenile polyposis." (PMID 24603803, 2014).
juvenile polyposis (continued). "Pathogenic variants in endoglin (ENG, chromosome 9q34), activin A receptor type II-like 1 (ACVRL1/ALK1, chromosome 12q13), and SMAD4 (chromosome 18q21) cause HHT1 (OMIM 187300), HHT2 (OMIM 600376), and combined Juvenile Polyposis/HHT (JP/HHT) syndrome (OMIM 175050), respectively." (PMID 41462841, 2025). "The majority (>85%) of HHT patients are heterozygous for loss of function (LOF) mutations in the endoglin (ENG, HHT1) or activin A receptor like type 1 (ALK1, HHT2) genes, whilst a minority (∼5%) carry mutations in the SMAD4 gene and show a combined juvenile polyposis and HHT phenotype." (PMID 36250069, 2022). "Endoglin (ENG, chromosome 9q34), Activin A receptor type II-like 1 (ACVRL1/ACVRL1/ALK1, chromosome 12q13), and MADH4/SMAD4 (chromosome 18q21) mutations cause HHT1 (OMIM 187300), HHT2 (OMIM 600376), and the combined Juvenile Polyposis/HHT (JP/HHT) syndrome (OMIM 175050), respectively." (PMID 28231770, 2017).
arteriovenous malformations (28 papers, 2012 to 2025). "A loss of function of BMP pathway components, such as Endoglin, Alk1 or Smad4, frequently results in arteriovenous malformations (AVMs), both in human patients suffering from HHT and in zebrafish and mouse models of the disease." (PMID 39656297, 2024). "Postnatal conditional deletion of Endoglin or ALK1 in mice leads to development of arteriovenous malformations, and has been associated with the development of HHT." (PMID 35954181, 2022). "A conditional knock out mouse model for HHT1 has revealed that the arteriovenous malformations (AVMs), induced upon ENG loss, appear to be the result of delayed vascular remodeling and inappropriate ECs proliferation responses." (PMID 30761306, 2019). "Together, these results suggest that it has either been difficult to distinguish primary from secondary effects caused by loss of Alk1/Endoglin signaling or that distinct mechanisms trigger arteriovenous malformations depending on the tissue and/or vascular bed analyzed." (PMID 39656297, 2024). "Insights generated from such studies can aid in finding out whether variability in EC shape also contributes to the onset of human arteriovenous malformations that occur due to a loss of Endoglin." (PMID 39213451, 2024). "In diseases such as arteriovenous malformations (AVMs), Alk1 or ENG (two key genes for AVMs) depletion induced higher-than-normal KLF2/4 expressions, and these increased levels were non-protective." (PMID 32502201, 2020). "Firstly, we checked for variants in ENG, NOTCH4, and TGFβR2 that are known to be involved in arteriovenous malformation development." (PMID 32560555, 2020). "Mutations in endoglin (ENG) and activin receptor-like kinase 1 (ACVRL1) genes are responsible for HHT1 and HHT2 and are associated with arteriovenous malformations." (PMID 25763011, 2015). "The majority of patients carry mutations in either Endoglin (ENG) or ACVRL1 (also known as ALK1) genes, and the disease is characterized by arteriovenous malformations and persistent haemorrhage." (PMID 24896812, 2014). "Mice in which endoglin has been depleted in ECs (Eng-iKOe mice) develop major arteriovenous malformations, but retain the ability to develop the deeper layers of the vascular plexus." (PMID 22745736, 2012). "Causative mutations in one of several genes, most commonly endoglin (ENG) or activin receptor-like kinase 1 (ACVRL1) and less commonly SMAD4, lead to the characteristic HHT lesions—large vessel arteriovenous malformations (AVMs) and/or small vessel telangiectases." (PMID 30191360, 2019). "Interestingly, both ALK1 and Endoglin exhibit similar endothelial expression patterns and both act within the same signaling pathway resulting in hereditary hemorrhagic telangiectasia disease and arteriovenous malformations." (PMID 26090377, 2014). "The role of endoglin in HHT-1 has been further illustrated for endoglin heterozygous (+/−) knock-out mice that develop symptoms similar to those seen in humans, such as arteriovenous malformations (AVMs)." (PMID 25080347, 2014). "Because RASA1 mutations have previously been associated with capillary and arteriovenous malformations similar to the HHT phenotype, and because no variants were identified in the ENG, ACVRL1, or SMAD4 genes, the RASA1 variant was assumed to be the causative mutation for this sample." (PMID 24268183, 2013).
renal carcinoma (26 papers, 2007 to 2025). A carcinoma arising from the epithelium of the renal parenchyma or the renal pelvis. "More interestingly, we observed human PECAM1/CD31 and ENG/CD105 expression in all tumor types, with higher rate in glioblastoma and renal cancer xenografts." (PMID 24625025, 2014). "Accordingly, all the endoglin-positive vessels in BM from pulmonary squamous cell carcinoma and renal carcinoma, displayed a mature phenotype, while vessels with an immature phenotype were found in highly vascularized BM from pulmonary large cell and adenocarcinoma." (PMID 24699047, 2014).
ovarian carcinoma (25 papers, 2009 to 2026). A malignant neoplasm originating from the surface ovarian epithelium. "Endoglin-targeting microbubbles were therefore associated with higher signal intensity than αvβ3-targeting microbubbles in ovarian cancer xenografts, whereas this pattern was reversed in pancreatic cancer xenografts." (PMID 22837657, 2012). "Similarly, ENG expression is associated with drug resistance, poor differentiation, advanced disease stage, and a high rate of recurrence in ovarian cancer patients." (PMID 33804796, 2021). "Endoglin has been proved to be involved in the development of cardiac valve and in the cell migration and invasion in endometriosis, ovarian cancer and clear cell renal carcinoma, all of which are achieved through regulation of the EMT process." (PMID 36210850, 2022). "ENG downregulation inhibits the proliferation and angiogenesis of human ovarian carcinoma-derived ECs, and it decreases the number of tumor-associated vessels and the growth of mammary adenocarcinomas in vivo." (PMID 33804796, 2021). "In fact, the negative regulation of ENG by miRNA-370 has been validated in ovarian cancer cells where miRNA-370 suppresses their proliferation and promotes chemosensitivity to cisplatin by negatively regulating ENG." (PMID 32899377, 2020). "Specifically, the TGF-β co-receptor endoglin (CD105) and the Hedgehog mediator Gli 1/2, which are overexpressed in recurrent ovarian cancers, both affect the viability of ovarian cancer cells, and Gli 2 also affects resistance to cisplatin." (PMID 23528891, 2013). "Consequently, ENG inhibition with small interfering RNA (siRNA) in ovarian cancer cells produces a less aggressive phenotype, with the induction of apoptosis and enhanced sensitivity to carboplatin in in vivo models." (PMID 33804796, 2021). "Evidence in ovarian cancer also suggests that endoglin expression may impact metastasis." (PMID 33819300, 2021). "Our previous study showed that the commercially available ovarian cancer cell lines ES-2 and OAW-42 expressed the markers characteristic for the mesenchymal stem cell markers CD73 (ecto-5′-nucleotidase), CD90 (Thy-1), and CD105 (endoglin)." (PMID 38791431, 2024). "CD44, as well as other CSC markers endoglin (CD105) and CD106 has been proved to be highly expressed in chemo-resistant ovarian cancer cells and in advanced-stage epithelial ovarian cancer tissues, suggesting CD44 may accelerate the progression of ovarian cancer by modulating the properties of CSCs." (PMID 31497537, 2019).
colorectal cancer (24 papers, 2003 to 2025). A primary or metastatic malignant neoplasm that affects the colon or rectum. "Endoglin is also reported to promote colorectal cancer liver metastasis by cancer-associated fibroblast (CAF)-expressing endoglin and TGF-β signaling." (PMID 35203627, 2022). "The expression of endoglin in CAFs of patients with stage II colorectal cancer correlates with increased development of metastases." (PMID 33800564, 2021). "This also correlates with data demonstrating that endoglin targeting inhibits metastatic spread in pre-clinical models for breast and colorectal cancer." (PMID 32059544, 2020). "Our study on colorectal cancer (CRC) shows that endoglin-expressing α-SMA+ CAFs at the invasive front of CRC, are related to metastasis-free survival." (PMID 32059544, 2020). "Furthermore, ENG has been shown to mediate the invasion of angiosarcoma and colorectal cancer cells." (PMID 38791148, 2024). "It has been reported that expression of the endoglin in tumor endothelium may be a prognostic indicator of the outcome for various human tumors including and colorectal cancer (CRC)." (PMID 27102733, 2016). "Moreover, MMP-9 regulated vascular endothelial growth factor-mediated neoangiogenesis of colorectal cancer, and MMP-mediated endoglin mobilisation plays a key role in the regulation of the angiogenic potential of endothelial cells in colorectal cancer." (PMID 26314959, 2015). "It has been reported that expression of the endoglin in tumor endothelium may be a prognostic indicator of the outcome for various humans tumors including and colorectal cancer (CRC)." (PMID 26089870, 2015). "Although M1043 is a stronger inhibitor of BMP-9 binding to mouse endoglin than it is to human endoglin, it does appear to be less potent than TRC105 in certain in vivo colorectal cancer models." (PMID 33375670, 2020). "Endoglin, a useful marker to identify human endothelial cells, did not stain any blood vessel, although it was expressed by the UBC cells; the same has also been observed in colorectal cancer cells." (PMID 36765947, 2023). "Moreover, in colorectal cancer (CRC), endoglin-expressing CAFs seem to contribute to metastatic potential and the formation of liver metastasis in an experimental model of CRC-derived liver metastases in nude mice." (PMID 33375670, 2020). "Interestingly, we previously observed that MMP-9 is involved in the VEGF-mediated neo-angiogenesis in colorectal cancer and that MMP-mediated endoglin mobilisation is involved in the regulation of the angiogenic potential of endothelial cells in colorectal cancer." (PMID 22472880, 2012).
glioblastoma (24 papers, 2012 to 2024). The most malignant astrocytic tumor (WHO grade IV). "We studied endoglin expression in glioblastoma tissue and in glioma-associated endothelial cells in a cohort of 52 newly diagnosed and 10 recurrent glioblastoma patients by immunohistochemistry and by ex vivo single-cell gene expression profiling of 6 tumors." (PMID 33471197, 2021). "In light of the central protumorigenic role attributed to TGF-β, the present study focused on the potential biological role of endoglin in glioblastoma." (PMID 33471197, 2021). "Protein levels of endoglin were determined by immunohistochemistry in 52 newly diagnosed and 10 recurrent glioblastoma tissue samples." (PMID 33471197, 2021). "Therefore, we investigated the association of endoglin with the hypoxia-responsive genes CAIX, VEGFA, VEGFR1, and VEGFR2 in glioblastoma samples from the TCGA database." (PMID 33471197, 2021). "However, little is known on the assessment of the expression levels of endoglin (CD105) during the glioblastoma progression in vivo." (PMID 30498402, 2018). "Molecular US imaging with the aid of targeted MBs is suitable for assessing the neovasculature progression of glioblastoma at the early stage by visualization of the proangiogenic biomarker endoglin (CD105), which is highly expressed on the neovasculature wall." (PMID 30498402, 2018). "Therefore, ENG has been proposed as a biomarker in glioblastoma." (PMID 33396280, 2020). "Finally, with the rationale of investigating the presence of endothelial markers in GBM cells and their regulation by hypoxia conditions, we found a significant induction of endothelial-related ENG, recently suggested as a relevant biomarker in glioblastoma and, in fact, nicely found in our GICs." (PMID 33396280, 2020). "Further, endoglin mRNA expression of a human cerebral microvascular endothelial cell line (hCMEC) and of CD31+ cells isolated from freshly dissociated human glioblastoma tissues was analyzed." (PMID 33471197, 2021). "Endoglin (CD105), as an alternative angiogenic factor on the luminal surface of glioblastoma neovasculature, is suitable to work as the binding target of ultrasound contrast agent." (PMID 30498402, 2018). "Endoglin (CD105), which is an alternative proangiogenic growth factor, has been remarkably upregulated on the proliferating glioblastoma neovasculature." (PMID 30498402, 2018). "FACS analysis showed that the glioblastoma CD133+ cells expressed the typical mesenchymal markers CD29, CD44 (hyaluronic receptor), CD73, CD90, CD105 (endoglin) and CD166." (PMID 27244897, 2016). "Understanding of the temporal and spatial expression levels of endoglin (CD105) in vivo could potentially contribute greatly to both the early diagnosis and anticancer therapy of glioblastoma." (PMID 30498402, 2018). "Endoglin expression was variable among glioma cell lines, with the highest expression levels in three LTC, A172, U87MG, and T98G, which was comparable with the levels of hCMEC and serially passaged CD31+ cells isolated from glioblastoma tissues; endoglin mRNA expression in GIC was low." (PMID 33471197, 2021). "This multicenter, open-label exploratory trial of anti-endoglin inhibitor TRC105 (carotuximab), with and without VEGF inhibitor bevacizumab (ENDOT), demonstrated expected safety and tolerability in patients with glioblastoma that have progressed after chemoradiation and VEGF inhibitor therapy." (PMID 37684373, 2023).